CR2 (complement C3d receptor 2)
Diseases named in the same sentence as CR2 in open-access papers (continued):
Sharing a sentence is not in itself a finding about the gene and the disease.
tumor (131 papers, 2008 to 2026). "We further validated the expression of CCDC50 and CR2 at the protein level using IHC, which confirmed their significant overexpression in tumor tissues." (PMID 38515748, 2024). "The previous work showed that adenoviral E1A with a CR2 portion deletion downregulated cell membrane receptor Her-2/neu expression and inhibited tumor progression in hepatocarcinoma xenografts model." (PMID 27340782, 2016). "In the SWI/SNF-mutant cohort, a seven-gene signature comprising CRIM1 (angiogenesis), VEGFC (lymphangiogenesis), BMP7 (tumor microenvironment regulation), NR1D2 (immune modulation), BMPR1B (tumor proliferation), CR2 (B-cell activation), and TAPBPL (antigen presentation) was ultimately retained." (PMID 41438758, 2025). "Furthermore, CD6 activation of T cells promotes TCR diversity 59, while CR2-mediated complement pathway activation enhances B cell-driven activation of tumor-specific CD8+ T cells in anti-tumor immunity." (PMID 38505619, 2024). "CR2 also plays a role in recognizing foreign DNA during immune defense responses, which may indicate that CR2 contributes to the immune surveillance of tumor cells." (PMID 36497424, 2022). "We found that the mRNA expression of C1QA, C1QB, C1QC, C5AR1, C3AR1, C1QR (CD93), CR1, CR2, CR3 (ITGAM), and CR4 (ITGAX) were positively associated with almost all kinds of tumor immune cells, including CD8+ T cells, CD4+ T cells, B cells, macrophages, monocytes and DCs." (PMID 34813686, 2022). "The mechanism underlying chemotherapy-mediated B cell switch was further investigated in a mouse model, which revealed that the production of ICOSL+B cells post-chemotherapy, and the anti-tumor immune response elicited by these cells was dependent on complement receptor type 2 (CR2) signaling." (PMID 33906694, 2021). "CR2 also binds C3 fragments deposited on the surface of tumor cells." (PMID 24212958, 2011). "Consequently, B-cells specific CR2 depletion abrogated the anti-tumour effects of doxorubicin." (PMID 39765018, 2025). "The mRNA level of CR2, INSL4, FGF5, RAET1L and TNFRSF13B was upregulated in LUAD tumor tissues compared with paired normal tissues whereas AGER was downregulated." (PMID 36294477, 2022). "Tumor samples with a positive HPV status expressed significantly higher levels of all of the B cell-related genes analyzed, namely, BLK, CD19, CR2, HLA-DOB, MS4A1 and TNFRSF17." (PMID 31623665, 2019). "The binding of EA1 to pRb protein through the CR2 region of E1A gene was required for adenovirus replication in normal cells rather than in tumor cells, and thus Ad5-Δ24 selectively replicate in tumor cells by deleting the CR2 region." (PMID 28460470, 2017). "Since the tumor cells often have dysfunctional RB, and uncontrolled cell cycle, deletion of CR2 region allows this engineered adenovirus to selectively replicate in tumor cells but not in quiescent normal cells." (PMID 23028626, 2012). "Finally, combination of antineoplastic mAbs with a Complement Receptor 2 (CR2)-Ab construct (CR2-Fc) significantly enhanced CDC of a human prostate cell line and improved the long-term survival of nude mice challenged with tumor cells." (PMID 24212958, 2011). "In this present work, we demonstrated that a mutant adenoviral E1A (mE1A) deletion of portion CR1 and CR2 (30-60aa and 120-127aa) can selectively inhibit tumor cell growth, but had no cytotoxic effect on normal cells, while the wild type E1A induced normal cells death dramatically." (PMID 27340782, 2016). "In this process, the absence of CAF_CCL21 also impairs complement-dependent CR2 activation of B_CD74, while the dysfunction of B_CD74 weakens CD6-dependent activation of CD8+ T cells, thereby attenuating their involvement in anti-tumor immunity." (PMID 38505619, 2024).
infection (111 papers, 2007 to 2026). The state of being infected such as from the introduction of a foreign agent such as serum, vaccine, antigenic substance or organism. "Given its role in immune response regulation, CR2 is a viable candidate susceptibility gene for infection." (PMID 40221769, 2025). "Found primarily in the lymphatic system and on B-cells, elevated levels of CR2 were associated with prior infection with SARS-CoV-2." (PMID 38565620, 2024). "In this study, we used RNA-seq analysis to profile the transcriptome of P. monticola primary needles during early stages of infection by C. ribicola; seedlings with major gene resistant (Cr2/-) and susceptible (cr2/cr2) genotypes were used." (PMID 24341615, 2013). "Moreover, binding of HIV-1 immune complexes to CR2 or CD21 on the surface of B cells has been linked to subsequent trans infection of T cells." (PMID 24278768, 2013). "The infection begins when the viral envelope glycoprotein gp350 binds to the complement receptor type 2 (CR2 or CD21) on the surface of B cells, facilitating viral entry." (PMID 39601114, 2024). "So, it is possible that one BL arises after the infection, and the virus would use the CR2 expressed at basal levels in the germinal center B cell." (PMID 39766110, 2024). "According to this mechanism, MYC translocation (and thus MYC deregulation) will occur stochastically at one or a few cells that will express more CR2 in its membrane, which in turn will lead to a more efficient infection." (PMID 39766110, 2024). "The glycoproteins gp350 and gp42 play an essential role in infection of B cells by binding to CD21 (also known as CR2) and MHCII (also known as HLA class II), respectively." (PMID 36630458, 2023). "Blocking antigen binding to complement receptor type 2 and 1 (CR2/CR1) prior to infection with FMDV significantly reduced the detection of viral proteins on FDCs and FMDV genomic RNA in spleen samples." (PMID 35512014, 2022). "The most abundant glycoprotein on the viral surface is gp350, which interacts with complement receptor 2 (CR2) or CR1 to initiate the infection of B cells." (PMID 36424667, 2022). "To understand the possible mechanism of inhibition of HCMV replication by pep-CR2, we looked at the cytoplasmic and nuclear localization of pp150 at late time post infection." (PMID 34835083, 2021). "The EBV gp350/220 membrane glycoprotein binds to the EBV receptor on B cells, CR2 (also known as CD21), which is essential for the process of infection and contributes to the cellular host range of EBV." (PMID 35111158, 2021). "Infection of B cells with EBV is initiated by binding of the EBV envelope protein gp350 to the complement receptor 2 (CR2)/CD21." (PMID 33808755, 2021). "Among these receptors, CR1 and CR2 on monocytes are involved in phagocytosis via interactions with the C3 complement during infection." (PMID 31616424, 2019). "The inflammatory cytokine TNFα which is induced by infection (e.g. with pathogenic Salmonella) induces expression of all complement related genes except C5, C8GH and CR2." (PMID 31888466, 2019). "As a control we examined mRNA expression of the EBNA2 activated target gene CD21 (CR2) and found that CD21 mRNA levels were increased as expected from day 1 post-infection." (PMID 29385536, 2018). "In the present study, we observed an increase in the gene expression for complement including C6, C4A, CR2, C3 at 8wks post infection." (PMID 27467147, 2016). "Infection with MM32.10 virus was enhanced 9-fold on the CR2+ cells and 7-fold on the ΔCT+ cells, compared with 24-fold in the equivalent SupT1/R5 assay." (PMID 21401915, 2011). "For example, CR2 has been implicated in HIV trapping, archiving and trans-infection of T cells mediated by B cells and FDCs." (PMID 21401915, 2011). "Infection with MM24.464 was enhanced 48-fold on the CR2+ cells and 40-fold on the ΔCT+ cells, compared with 189-fold in the equivalent SupT1/R5 assay." (PMID 21401915, 2011).
infection (continued). "The complement system constantly interacts with HIV during all stages of infection highlighting the importance of CR2 in C-ADE." (PMID 19671191, 2009). "However, we do not exclude that longer persistence of the virus on FDCs after natural infections, when anti-virus antibody forms, are due to a combination of FcR and CR2/CR1 binding." (PMID 35512014, 2022). "Similarly, infection of CD4+ T cells is facilitated by circulating B cells that carry HIV bound to CR2." (PMID 19671191, 2009). "It has also been shown that targeted complement inhibition with CR2-Crry does not impair host susceptibility to infection, unlike systemic inhibition of C3 deficiency, a potentially important consideration for stroke patients who are at increased risk of infection." (PMID 26322048, 2015). "In addition to B cells and FDCs, CR2 expression has been reported on T cell subsets, thymocytes and astrocytes, which may support directly enhanced infection by HIV." (PMID 21401915, 2011). "Mechanistically, C'-ADE could occur by increasing physical attachments between the virus and the target cell, or through CR2-mediated signalling events leading to enhanced infection via an alternative route of entry, enhanced viral replication, or suppression of intracellular antiviral responses." (PMID 21401915, 2011). "During the primary infection of B cells, viral glycoprotein (gp) 350 binds to the cluster of difference 21 (CD21, also known as complement receptor II or CR2) located on the cellular surface." (PMID 33102204, 2020). "On the other hand, 24 genes were significantly upregulated by infection in the R line of the HSF flock, such as CD19, CD22, CD79B, two complement-related genes CFI and CR2 (complement C3d receptor 2), FGG, and FGA (fibrinogen alpha chain)." (PMID 30678719, 2019). "Interaction between gp350/220 and complement receptor type 2 (CR2)/CD21 and/or (CR1)/CD35 on B-cells is required for infection." (PMID 25885535, 2015). "Complement component receptor-2 (CR2, Hs.73792) is the membrane protein on B lymphocytes to which the Epstein-Barr virus (EBV) binds during infection of these cells." (PMID 17559667, 2007). "In B lymphocytes, upon infection, EBV gp350 interacts with complement C3d receptor 2 (CR2), located on the surface of B cells, followed by EBV gp42 binding with major histocompatibility complex (MHC) class II molecules, culminating in the fusion of the virus and cell membrane." (PMID 34944437, 2021). "Mice with depleted complements, or lacking B cells, FcγR1, CR1, CR2, or Nox2 (a subunit of NADPH oxidase) are more susceptible to non-lethal dose infection with the HF strain of Ehrlichia (Ixodes ovatus Ehrlichia) that is closely related to E. chaffeensis." (PMID 24098122, 2013). "In hindsight, however, this property could have been deduced from one of the first descriptions of how a lymphocyte was reprogrammed, i.e., after infection with Epstein-Barr virus (EBV) through its unique receptor, CR2/CD21." (PMID 23194300, 2012). "Infection experiments were performed in 24-well plates in triplicate and virus opsonization was performed by incubating appropriate dilutions of HIV in culture medium with normal human serum (NHS) and purified CR2-Fc proteins." (PMID 19671191, 2009). "Recently, a higher-throughput fluorescent imaging assay (FIA) using Akata-EBV-GFP to infect SVK-CR2 cells (an epithelial cell line overexpressing CR2) was reported, but it may not truly reflect the natural infection process." (PMID 36424667, 2022). "A cytometry adhesion inhibition assay was performed with sera from individuals suffering P. vivax malaria to determine whether the antibodies produced during natural infection could inhibit functional conserved regions (CR1 and CR2) interaction with reticulocytes." (PMID 28526096, 2017).
infection (continued). "This is in line with our results where neutralising antibody responses up to day 7 post infection were similar in mice with or without a CR2/CR1 block, yet after this timepoint, there was a significant reduction in FMDV neutralising antibodies in mice treated with the anti-CR2/CR1 mAb." (PMID 35512014, 2022).
cancer (31 papers, 2006 to 2025). A tumor composed of atypical neoplastic, often pleomorphic cells that invade other tissues. "In fact, as an example, the miR-122a-meadiated regulation via three miR-122a target sites downstream E1A gene and another regulation approach based on CR2-deletion targeting to Rb-deficient cancer cells has been successfully combined to fine-tune oncolytic adenoviruses." (PMID 21814544, 2011). "Thus, a deletion mutation, dl922-947, within CR2 permits virus replication in a broad range of cancer cells with abnormalities in cell-cycle checkpoints." (PMID 20211016, 2010). "Illuminating the mechanisms that regulate the development of central and peripheral FDCs, their CR2 levels and other functions will advance the understanding of the role of the follicular stroma in B cell responses to immunizations, infections and cancers." (PMID 37443283, 2023). "SEMA3A was downregulated in all the cancers in which it was differentially expressed, while the regulation of CR2 and MS4A1 varied according to cancer type." (PMID 36497424, 2022). "We found that C3AR1 expression is higher in GBM as compared with all other cancers analyzed in TCGA, whereas Complement Receptor 1 (CR1), CR2, C1qR1 (CD93), and C5AR1 were expressed at varying levels." (PMID 39172519, 2024). "This chemokine was combined with CR2 and activated the JAK/STAT3 pathway, which awakened the dormant cancer cells and promoted cancer progression clinically." (PMID 35634311, 2022). "Differential expression analysis with the limma-voom pipeline highlighted multiple genes, CR2, MS4A1, and SEMA3A, which should be further analyzed, given their prevalence among multiple cancer types." (PMID 36497424, 2022). "We found some downregulated proteins in MM-PC that seem to play important role in cancer immune evasion mechanisms such as: HLA-A, HLA- DRB5, CR1, and CR2." (PMID 26807199, 2015). "Several studies have shown that CR2-positive B cells are related to TLS formation and cancer prognosis, but the underlying mechanism has not been explored in depth." (PMID 38764038, 2024). "Additionally, volcano plots of the differentially expressed genes in these cancers indicated that in the RAC1 low-expression group, the expression levels of B cell surface markers (such as CD19, CD79A, and MS4A1) and immunoglobulin-related genes (such as IGHG1 and CR2) were higher." (PMID 39898257, 2025). "While the pan-cancer analysis did not demonstrate statistical significance for CCDC50 and CR2, the trend of gene overexpression was consistent." (PMID 38515748, 2024).
bacterial infections (2 papers, 2020 to 2021). "On the other hand, complement proteins were essential in MCs activation during bacterial infections, mainly through the CD21/CD35 (CR2/CR1) receptors." (PMID 34211473, 2021).
neurological diseases (2 papers, 2012 to 2019). "CR2-Crry-mediated targeting complement inhibition will alleviate the local inflammation and provide an effective treatment for the severe neurological diseases associated with EV71 infection." (PMID 23173749, 2012).
adenocarcinoma (1 paper, 2021). A common cancer characterized by the presence of malignant glandular cells. "This study aimed to identify novel genetic variants in the CR2 extracellular domain of the epidermal growth factor receptor (EGFR) in healthy individuals and patients with six different types of adenocarcinoma, in Arabian peninsula populations." (PMID 33874989, 2021).
neurodegenerative disease (1 paper, 2017). A disorder of the central nervous system characterized by gradual and progressive loss of neural tissue and neurologic function. "Hence, more studies are needed to gauge the functional role of CR2 in neuroinflammation, microglia in particular, especially with respect to human neurodegenerative diseases such as AD." (PMID 28878260, 2017).
CR2 also shares sentences with these, for which no sentence is quoted: malaria (21 papers); follicular dendritic cell sarcoma (10); B-cell chronic lymphocytic leukemia (7); Immunodeficiency (7); MALT lymphoma (7); Splenomegaly (7); lymphopenia (6); melanoma (6); diffuse large B-cell lymphoma (5); T-cell lymphoma (5); colorectal cancer (4); follicular lymphoma (4); meningioma (4); renal disease (4); Sjogren syndrome (4); AIDS (3); anaemia (3); Cerebral ischemia (3); colitis (3); hypogammaglobulinemia (3); infectious mononucleosis (3); inflammatory myofibroblastic tumor (3); leiomyosarcoma (3); leukemia (3); Lymphadenopathy (3); non-Hodgkin lymphoma (3); primary immunodeficiency (3); sarcoidosis (3); scrapie (3); spindle cell neoplasm (3).
A further 113 diseases each share a sentence with CR2 in 3 papers or fewer.